EIF2B5 (eukaryotic translation initiation factor 2B subunit epsilon)
Description:
Acts as a component of the translation initiation factor 2B (eIF2B) complex, which catalyzes the exchange of GDP for GTP on eukaryotic initiation factor 2 (eIF2) gamma subunit. Its guanine nucleotide exchange factor activity is repressed when bound to eIF2 complex phosphorylated on the alpha subunit, thereby limiting the amount of methionyl-initiator methionine tRNA available to the ribosome and consequently global translation is repressed.
Synonyms: EIF2Bepsilon; EIF-2B; CACH; CLE; LVWM; VWM5
Tractability: Small molecule: a structure with a bound ligand is known. PROTAC: UniProt records ubiquitination sites on it; ubiquitination databases record sites on it; its protein half-life has been measured.
Gene: Protein-coding gene on chromosome 3 (184,135,038 to 184,146,127, forward strand). Ensembl gene ENSG00000145191.
Subcellular location: Cytoplasm, cytosol
Subcellular location (Human Protein Atlas): Cytosol
Pathways (Reactome):
Metabolism of proteins: Recycling of eIF2:GDP
Gene Ontology:
Molecular function: guanyl-nucleotide exchange factor activity; protein binding; translation initiation factor activity; translation initiation factor binding
Biological process: astrocyte development; astrocyte differentiation; cytoplasmic translational initiation; myelination; oligodendrocyte development; ovarian follicle development; positive regulation of translational initiation; response to endoplasmic reticulum stress; response to heat; T cell receptor signaling pathway; translational initiation; response to glucose; response to peptide hormone; hippocampus development; positive regulation of apoptotic process; positive regulation of translation; regulation of translational initiation
Cellular component: cytoplasm; cytosol; eukaryotic translation initiation factor 2B complex; nucleus
Genetic constraint (gnomAD): Loss-of-function variants: 38 observed, 91.56 expected, observed/expected ratio (o/e) 0.42, 90% interval 0.32 to 0.54. The upper end of that interval is the gene's LOEUF score, 0.54, which puts it in group 2 of 6, group 1 being the genes least tolerant of losing a copy. Missense variants: 784 observed, 938 expected, observed/expected ratio (o/e) 0.84, 90% interval 0.79 to 0.89. Synonymous variants: 313 observed, 346.41 expected, observed/expected ratio (o/e) 0.9, 90% interval 0.82 to 0.99.
Gene-disease validity (ClinGen):
ClinGen rates the evidence that EIF2B5 causes each of these diseases.
leukoencephalopathy with vanishing white matter 5 (autosomal recessive): Definitive.
Homologues: Orthologues: chimpanzee EIF2B5 (99% identical), macaque EIF2B5 (98% identical), dog EIF2B5 (93% identical), rabbit EIF2B5 (91% identical), pig EIF2B5 (90% identical), rat Eif2b5 (88% identical), mouse Eif2b5 (88% identical), guinea pig EIF2B5 (87% identical), tropical clawed frog eif2b5 (66% identical), zebrafish eif2b5 (55% identical), Drosophila melanogaster eIF2Bepsilon (29% identical), Caenorhabditis elegans eif-2Bepsilon (24% identical). Paralogues in human: GMPPA (13% identical), GMPPB (12% identical), EIF2B3 (11% identical).
Diseases named in the same sentence as EIF2B5 in open-access papers:
EIF2B5 is named in the same sentence as 41 diseases in open-access papers, as found by Europe PMC text mining. Sharing a sentence is not in itself a finding about the gene and the disease. The quoted sentences say what the papers report.
ovarioleukodystrophy (6 papers, 2020 to 2026). The "ovarioleukodystrophies" comprise a group of rare leukodystrophies associated with primary or premature ovarian failure. "This case report presents a case of sudden progression of adult-onset ovarioleukodystrophy associated with compound heterozygous EIF2B5 mutations." (PMID 35785335, 2022). "The present study compiled the cases of ovarioleukodystrophy caused by EIF2B5 gene mutations, but certain cases were caused by other gene mutations." (PMID 35785335, 2022). "Here, we report a patient with an adult‐onset ovarioleukodystrophy carrying two novel disease‐causing variants in EIF2B5 identified by WES, one of which is an intronic mutation leading to activation of a cryptic splice donor site." (PMID 33245593, 2020). "Previous studies that compiled cases of ovarioleukodystrophy due to EIF2B5 variants have shown that the p.Arg113His variant is the most frequent, whether it is in a homozygous or compound heterozygous state." (PMID 41244982, 2025). "Literature review for female late-onset ovarioleukodystrophy due to the EIF2B5 gene mutation." (PMID 35785335, 2022). "Furthermore, the present report summarizes 20 female patients with adult-onset ovarioleukodystrophy and EIF2B5 gene mutations." (PMID 35785335, 2022). "Furthermore, the up-to-date clinical features about late-onset ovarioleukodystrophy associated with EIF2B5 gene mutations were reviewed." (PMID 35785335, 2022). "Therefore, ovarioleukodystrophy caused by EIF2B5 gene mutations should be a variant phenomenon of LVWM." (PMID 35785335, 2022). "Other not EIF2B5 gene variants ovarioleukodystrophy cases are not included either." (PMID 35785335, 2022). "Thus, our work is the first functional validation report of a novel, noncanonical splicing mutation in EIF2B5 associated with ovarioleukodystrophy." (PMID 33245593, 2020).
colorectal cancer (5 papers, 2016 to 2025). A primary or metastatic malignant neoplasm that affects the colon or rectum. "High EIF2B5 expression was associated with worse survival of colorectal cancer patients." (PMID 36100884, 2022). "Eukaryotic translation initiation factor 2B, subunit 5 epsilon, (EIF2B5) is highly expressed in lung and breast cancers and is also a biomarker for colorectal cancer." (PMID 40746880, 2025). "EIF2B5 is an oncogene with maximal expression in stage 3, again according with its identified role as a major hub driver gene for progression to advanced stages of colorectal cancer." (PMID 39484215, 2024). "In addition, dysregulated EIF2B5 expression was also corrected with the progression of liver cancer, colorectal cancer and diffuse large B-cell lymphoma." (PMID 36100884, 2022). "Furthermore, depletion of EIF2B5 facilitated MYC-driven apoptosis of colorectal cancer SW480 cells." (PMID 36100884, 2022).
leukodystrophy (4 papers, 2018 to 2025). Leukodystrophies are a group of rare, progressive, metabolic, genetic diseases that affect the brain, spinal cord and often the peripheral nerves. "Mutations in EIF2B5 impair the regulation of protein synthesis during cellular stress, leading to vanishing white matter disease, a progressive leukodystrophy characterised by neurological deterioration." (PMID 41300791, 2025). "Whole-exome sequencing testing revealed a novel pair of compound heterozygous variants in the EIF2B5 gene, confirming the diagnosis of leukodystrophy with VWM and bringing an end to a nearly 20-year diagnostic odyssey." (PMID 41244982, 2025). "Whole-exome sequencing revealed a novel pair of compound heterozygous variants in the EIF2B5 gene, confirming the diagnosis of leukodystrophy with VWM and bringing closure to a nearly 20-year diagnostic odyssey." (PMID 41244982, 2025). "Here, whole-exome sequencing was conducted based on the clinical and imaging suspicion of leukodystrophy revealing a novel pair of compound heterozygous missense variants (p.Leu106Phe and p.Arg563Gln) in the EIF2B5 gene, supporting the diagnosis of VWM in the proband." (PMID 41244982, 2025).
Leukoencephalopathy (4 papers, 2018 to 2025). This term describes abnormality of the white matter of the cerebrum resulting from damage to the myelin sheaths of nerve cells. "The Eif2b5 mouse model replicates Cree leukoencephalopathy caused by a homozygous p.Arg195His variant in EIF2B5." (PMID 40326783, 2025).
head and neck cancer (3 papers, 2017 to 2024). A primary or metastatic malignant neoplasm affecting the head and neck. "Specific retention of intron 12 in EIF2B5 led to a previously undescribed 65kDa isoform of eIF2Bε that decreases overall protein synthesis in head and neck cancer cells." (PMID 28961236, 2017). "On the contrary, hypoxia-induced SRSF3 promotes specific retention of intron 12 in EIF2B5, resulting in EIF2B5 protein decrease by the NMD pathway; therefore, inhibiting overall initiation of translation to protect head and neck cancer cells from extreme hypoxia, ensuring cell survival." (PMID 38778254, 2024).
liver cancer (3 papers, 2020 to 2023). An epithelial or non-epithelial malignant neoplasm that arises from the liver. "Enhanced EIF2B5 expression could indicate poor prognosis of liver cancer patients." (PMID 36100884, 2022).
ovarian carcinoma (3 papers, 2022 to 2025). A malignant neoplasm originating from the surface ovarian epithelium. "Our findings evidenced that lncRNA KCNQ1OT1 aggravated ovarian cancer metastasis by decreasing EIF2B5 expression level, and provided a novel therapeutic strategy for OC." (PMID 36100884, 2022).
Ataxia (2 papers, 2025 to 2026). Ataxia refers to impaired coordination of voluntary muscle movement. "A literature review of 99 genetically confirmed adult-onset VWMD cases further underscores genotype-phenotype correlations: EIF2B5 is the most frequently mutated subunit in adult patients, with cerebellar ataxia, cognitive decline, and psychiatric symptoms as the predominant initial manifestations." (PMID 41700296, 2026). "At age 9 months, we found that astrocyte-specific Eif2b5 conditional mice showed very mild ataxia, extensive intramyelinic vacuolization, normal density and maturity of oligodendrocytes, and high expression of ATF4-related genes." (PMID 40326783, 2025). "Oligodendrocytes are the major contributors to the development of ataxia, but astrocyte-specific Eif2b5 conditional mice display several histological and molecular key features of VWM." (PMID 40326783, 2025).
microcephaly (2 papers, 2020 to 2023). A congenital or acquired developmental disorder in which the circumference of the head is smaller than normal for the person's age and sex. "We report herein for the first time autopsy findings in two foetal siblings interrupted at 27 and 32 weeks of gestation (WG) for microcephaly with cerebellar hypoplasia, which harbored two compound heterozygous pathogenic variants in the EIF2B5 gene, one of the two being novel." (PMID 32293553, 2020).
Gait ataxia (1 paper, 2025). A type of ataxia characterized by the impairment of the ability to coordinate the movements required for normal walking. "Oligodendrocyte-specific Eif2b5 conditional mice developed gait ataxia that matched the phenotype of the whole-body Eif2b5 mutant line." (PMID 40326783, 2025).
major depressive disorder (1 paper, 2018). An episode of depression lasting two or more weeks without an intervening episode of mania. "In our study, novel chr3:183874023 variant within the locus for major depressive disorder was matched to EIF2B5 gene." (PMID 29745862, 2018).
ovarian disorder (1 paper, 2025). A disease involving the ovary. "Pathogenic variants in the EIF2B5 gene, which encodes the epsilon subunit of the eukaryotic translation initiation factor 2B (eIF2B), are associated with autosomal recessive leukodystrophy with VWM, which is frequently—but not invariably—accompanied by ovarian disorder in females." (PMID 41244982, 2025).
cancer (13 papers, 2015 to 2024). A tumor composed of atypical neoplastic, often pleomorphic cells that invade other tissues. "Their elevated expression is associated with decreased promoter methylation at cancer stages 2, 3, and 4, as well as copy number amplifications in EIF2A and EIF2B5 genes." (PMID 38001610, 2023). "A previous study showed that IR in the master regulator of translation initiation factor, namely EIF2B5, creates a stop codon that inhibits global translation to cope with hypoxia stress in cancer cells, or IR regulates gene expression programs." (PMID 35637454, 2022). "The physiological relevance of these findings is underscored by the fact that EIF2B5 intron 12 is overexpressed in tumor versus normal tissues of patients affected by 6 different cancers, including HNSC." (PMID 28961236, 2017). "We then looked at the hub-driver genes identified in a previous study of CRC network analyses (Palaniappan, Ramar & Ramalingam, 2016), and found that GRIN2A and EIF2B5 were significantly differentially expressed in the cancer samples (adj.p-values ∼2.14e−37 and 2.32e−13, respectively)." (PMID 39484215, 2024). "Notably, a retained intron in EIF2B5 contained a premature termination codon impedes global translation, allowing cancer cells to adapt to a hypoxic environment." (PMID 38303029, 2024). "Thus, we propose that, during periods of acute or prolonged hypoxia, intron retention in EIF2B5 leads to expression of a truncated dominant-negative isoform to further inhibit protein synthesis in cancer cells." (PMID 28961236, 2017).
tumor (6 papers, 2015 to 2024). "EIF2B5 was disclosed to modulate the initial stage of protein synthesis, that could expedite angiogenesis and tumor growth." (PMID 36100884, 2022).
infection (2 papers, 2011 to 2021). The state of being infected such as from the introduction of a foreign agent such as serum, vaccine, antigenic substance or organism. "Several transcription factors such as E2F transcription factor 1, EIF3S9, and EIF2B5, are down-regulated early in the infection and then up-regulated later in the infection." (PMID 22087245, 2011).
neurologic disease (2 papers, 2021). "MCL-1 protein abundance was reduced in eif2b5-mutant mouse model of the leukodystrophy vanishing white matter disease (VWMD), suggesting the potential for MCL-1 deficiency to contribute to clinical neurologic disease." (PMID 34873168, 2021).
EIF2B5 also shares sentences with these, for which no sentence is quoted: leukoencephalopathy with vanishing white matter (7 papers); breast carcinoma (2); cardiac hypertrophy (2); atrial fibrillation (1); brain disorder (1); cerebellar ataxia (1); Cerebroretinal vasculopathy (1); cognitive decline (1); colorectal tumors (1); dementia (1); epilepsy (1); heart failure (1); hypertrophy (1); hypospadias (1); injury (1); left ventricular hypertrophy (1); metachromatic leukodystrophy (1); neuromuscular disease (1); Onset (1); ovarian failure (1); pontocerebellar hypoplasia, type 1C (1); prion disease (1); syndromic epilepsy (1); type 2 diabetes (1); viral infection (1).